MYC (MYC proto-oncogene, bHLH transcription factor)
Diseases named in the same sentence as MYC in open-access papers (continued):
Sharing a sentence is not in itself a finding about the gene and the disease.
tumor (continued). "The benzoisoxazoloazepine CPI-0610 decreased MYC transcripts in vivo and reduced leukemia xenograft tumor growth, which was synergistic with doxorubicin treatment." (PMID 35008680, 2021). "Cancer-associated hypomethylation occurs also in several tumor-initiator or proliferation-associated genes, such as pS2gene, HOX11 proto-oncogene, and c-MYC and c-N-ras oncogenes." (PMID 34199020, 2021). "We used the model’s estimated parameter values for each mouse to predict the amount of tumor burden in the doxycycline-sensitive (MYC-On and MYC-Off) and doxycycline-resistant (Escaped) states." (PMID 33446671, 2021). "In lung cancer, deregulation of miRNA expression is a common mechanism through which tumours modulate the activity of critical oncogenes and tumour suppressors, including MYC and PTEN." (PMID 34072436, 2021). "We should note, however, that c-MYC, a member of the LEDGF/p75 interactome, has already been implicated as a driver of tumor aggressiveness, stemness, and chemoresistance in various cancer types, including PCa." (PMID 34685704, 2021). "MYC signalling also increases the dependency on glutamine metabolism and uptake in basal-like tumours, characterized by high glutaminase (GLS) and low GS levels." (PMID 34572926, 2021). "Beyond the regulation of major signaling molecules, PKD also regulates transcription factors that are critical for tumor cell proliferation, such as c-MYC and class IIa HDACs." (PMID 33807058, 2021). "Previous study revealed that circulating tumor cells (CTCs) in PCa patients have recurrent MYC gene amplification." (PMID 34335968, 2021). "A small hybrid protein named ME47 can also inhibit MYC transcriptional activity by seizing the E-box binding site of MYC target genes, resulting in a significant reduction in cell proliferation of tumor xenografts." (PMID 34372899, 2021). "A significant increase was observed in the expression of LGR5 (p: 0.01) and PROM1 (p: 0.005) genes in villous HGD polyps, LGR5 (p: 0.003) gene in G1, and LGR5 (p: 0.0002) and MYC (p: 0.002) genes in G2 stage tumor tissues." (PMID 34452555, 2021). "Characterized as a driver of tumor biological functions, MYC overexpression frequently predicts a poor clinical outcome and an aggressive course of disease." (PMID 34930894, 2021). "PLA2R1 is down-regulated in a number of cancer types, which supports its tumor suppressor role, and its expression can be suppressed by c-MYC and HIF2α, the oncogenes." (PMID 34112138, 2021). "Cells that overexpress MYC take on characteristics of tumour cells, proliferating and growing more rapidly, whilst ablation of MYC results in the opposite effect." (PMID 33799592, 2021). "The role of MYC as a regulator of the tumour microenvironment, in addition to its intrinsic effects on cancer cells, is emerging." (PMID 34847775, 2021). "When administered to a MYC-driven liver tumor model by IV injection, modular degradable dendrimer nanoparticles carrying let-7g miRNA mimic have been shown to inhibit tumor growth and dramatically extended mouse survival." (PMID 34572067, 2021). "The gross genetic changes at MYC locus, including insertional mutagenesis, chromosomal translocation, and gene amplification would lead to the phenotype of Myc deregulation in tumor." (PMID 33692331, 2021).
tumor (continued). "Incidentally, glutamate cysteine ligase (GCL), the rate-limiting enzyme of GSH synthesis, was markedly decreased in MYC-driven murine tumor samples, which contributed to decreased glutamine incorporation into GSH." (PMID 34503295, 2021). "In this assay, therefore, the MYC–HCF-1 interaction is required for tumor growth, and there is little if any difference between disruption of the MYC–HCF-1 interaction and disabling the majority of the nuclear functions of MYC." (PMID 33416496, 2021). "While further research is needed to identify drug candidates, these findings reveal a promising target for treating tumours that stem from over-abundant MYC proteins." (PMID 33416496, 2021). "Subsequently, H1299/R cells where LINC01001 was overexpressed and MYC was inhibited were subcutaneously injected into BALB/C nude mice for tumor information (n = 7)." (PMID 34630126, 2021). "They demonstrated a blockage in proliferation and enhanced apoptosis by decreasing the phosphorylation of RNA Polymerase II, reduction of MCL-1 and MYC proteins and MYC downregulation, resulting in a very significant tumor burden reduction." (PMID 35582389, 2021). "In tumor cells, the expression of c-MYC has been shown to significantly decrease after the JPH203-mediated inhibition of SLC7A5, thereby affecting the metabolic function controlled by c-MYC." (PMID 34977008, 2021). "Oncogenic deregulation of MYC expression produces cells with tumor phenotype during normal development." (PMID 34452555, 2021). "On the other hand, case 14S revealed mostly gains of COX2, DBC2 and MYC in more than 90% of the tumor cells." (PMID 34282768, 2021). "Simultaneous inhibition of CDK7 and CDK12/13 with THZ1 abrogates c-MYC expression and decreases tumor growth in platinum- and PARP inhibitor-resistant patient-derived xenograft (PDX) models of HGSOC." (PMID 33718147, 2021). "Another miRNA overexpressed in ccpRCC, miR-34a, was previously indicated to suppress c-MYC and its complexes as well as to prevent cell invasion, thus acting as a tumour suppressor." (PMID 35008576, 2021). "FBXW7, a critical tumor suppressor in many types of cancer, regulates the proteasome-mediated degradation of oncoproteins including MYC." (PMID 33494392, 2021). "Tumoral levels of MYC lead to its stronger interaction with binding sites of genes that in normal conditions weakly bind MYC and that codify for G-protein coupled receptors and for proteins engaged in nutrient transport and hypoxic response." (PMID 33801599, 2021). "MYC: Myc is well recognized for its oncogenic role in PCa progression and as a modulator of tumor metabolism." (PMID 34948229, 2021). "Another important protein for the BECN1-containing complex activity, AMBRA1, is reported to act as a tumor suppressor via facilitating the degradation of the proto-oncogene MYC/c-Myc." (PMID 34829881, 2021). "MYC also regulates tumor microenvironment through activation of angiogenesis and suppression of the host immune response." (PMID 33801599, 2021). "Since suppression of MYC expression can reduce cell resistance to chemotherapy and radiotherapy, the use of tumor-specific MYC inhibitors can be applied to create effective anti-tumor therapy options." (PMID 34440124, 2021). "For example, a gain in semaphorin 4D was shown to support tumor cell transmigration through the blood–brain barrier and MYC has been suggested as a key factor for the adaptation of disseminated tumor cells to the activated brain microenvironment." (PMID 35008251, 2021). "We found that the expression of UGT2B4 was positively associated with expression of multiple well-known oncogenes such as SPINK1, IDH1, MYC, and SRC and negatively associated with expression of well-known tumor suppressors such as CIC and ERF." (PMID 33391440, 2021). "PC levels were also increased in MYC-activated lung tumor tissue, compared to inactivated tumor tissue." (PMID 34439333, 2021).
tumor (continued). "MYC plays an important role in re-programming the tumor microenvironment, especially the inflammatory and immune components of tumor stroma." (PMID 34829869, 2021). "A recent study has demonstrated the antitumor activity of small molecule MYC inhibitors (MYCi361 and MYCi975), resulting in suppressed tumor growth and tumor sensitization to immune checkpoint inhibition in vivo." (PMID 34885165, 2021). "These tumors were found to be dependent on MYC amplification and subsequent inactivation of MYC saw tumor regression in an NK cell-dependent manner." (PMID 33917037, 2021). "MYC, is one of the most important drivers of tumor development and has been emphasized as a key therapeutic target for cancer treatment of multiple cancer types." (PMID 34630126, 2021). "In mice treated with osimertinib, MYC/myrAKT markedly accelerated acquired treatment resistance in both tumor models." (PMID 34656143, 2021). "Another effect mediated by PLD6-dependent mitochondrial fusion is also the increase in the levels of glutaminolysis, an essential process for tumor survival since MYC-driven cell growth depends on glutamine." (PMID 33920160, 2021). "Using genetic and pharmacologic approaches, we found that combined inhibition of MYC transcription (by BET protein inhibition) and mTOR signaling had a synergistic anti-tumor effect against MYC-driven group 3 MB." (PMID 35054230, 2021). "Alternatively, synthetic lethal approaches provide promise to selectively kill tumor cells that overexpress MYC while sparing normal somatic cells." (PMID 33760847, 2021). "As let-7 target c-MYC and MYCN and LIN28B is a transcriptional target of both c-MYC in multiple human and mouse tumor models and MYCN in NB, the inhibition of let-7 is c-MYC/MYCN-mediated via LIN28." (PMID 34771690, 2021). "In logistic regression models, including clinical stage, tumor volume on biopsy, and presence of CRIB/IDC, cases with MYC gain and PTEN loss remained at higher risk for NOCD (odds ratio, 6.23; 95% CI, 1.74–24.55; P = 0.005)." (PMID 34062284, 2021). "We show that MYC activates PLK1 transcription, while the inhibition of PLK1 suppresses MB tumor development and causes a decrease in c-MYC protein level by suppressing FBXW7 auto poly-ubiquitination." (PMID 33494392, 2021). "We have previously identified two CSC subpopulations within mHNcSCC: an OCT4+/SOX2+/NANOG+/KLF4+/c-MYC+ subpopulation within the tumor nests (TNs) and an OCT4+/SOX2+/NANOG-/KLF4+/c-MYC+ subpopulation within the peritumoral stroma (PTS)." (PMID 34621666, 2021). "(A) The percentage of tumor samples with ZHX2 (top) or MYC (bottom) focal amplification across cancer types." (PMID 34779768, 2021). "FBXW7 is a key substrate recognition subunit of the SCF complex that acts as a tumor suppressor gene by controlling the proteasome-mediated degradation of oncoproteins, such as c-MYC, MCL1, Notch1/4, cyclin E, and mTOR." (PMID 33676554, 2021). "Inhibition of proteasomal destruction by O-GlcNAcylation would lead to stronger MYC activity and tumor progression." (PMID 34868034, 2021). "In comparison, the MYCN locus was present at a 2-copy state with two signals detected for both MYCN and the centromere of chromosome 2 (primary tumor: nuc ish(MYCNx2)[89/100]), recurrent tumor: nuc ish(MYC amp)[87/100])." (PMID 34895332, 2021). "All patients in this study were required to have tumour harbouring some level of MYC expression or MYC translocation; however, despite this requirement, most patients did not demonstrate response." (PMID 33311588, 2021). "MiR-184 has been shown to inhibit MYC expression and tumor cell proliferation in response to increased levels of the tumor suppressor PDCD4." (PMID 34440124, 2021).
tumor (continued). "In a mutant KRAS lung adenocarcinoma model, conditional MYC amplification led to increased expression of IL-23 by tumor cells that inhibited recruitment of intra-tumoral B, T and natural killer (NK) cells." (PMID 33917037, 2021). "This dramatic inhibition of tumor growth by the combined treatment occurred through synergistic suppression of MYC, which induced apoptotic regulators thereby markedly promoting tumor apoptosis." (PMID 34761120, 2021). "In conclusion, this study revealed that MYC-induced transformation of Sox2+/Aldh1a1high cells led to tumour growth in the postnatal cerebellum in vivo, with characteristics of type 3 medulloblastoma." (PMID 34445233, 2021). "A high level of miRNA suppressing MYC expression can be combined with a high level of transcription of this proto-oncogene in tumor cells due to ceRNA, which binds and inactivates certain miRNAs." (PMID 34440124, 2021). "Whilst it might appear counterintuitive that increased MYC can lead to increased apoptosis in the context of tumourigenesis, the associated upregulation of oncogenic pro-survival proteins to counter this effect is a prominent feature of the development of some tumours." (PMID 33799592, 2021). "Depletion of MYC in 23 cell lines with short-hairpin in a systematic study led to cell cycle arrest in G0/G1 in normal and some tumor-derived cell lines, whereas G2/M arrest happened in other tumor-derived cell lines." (PMID 34372899, 2021). "Combined treatment with CisPt + RSV acted differently on c-MYC expression in the two tumor cell lines." (PMID 34204834, 2021). "Common somatic gene mutations that regulate cellular and energy metabolism in breast cancers, such as observed in RB1 and MYC genes, demonstrate variable clonal frequencies within a tumour, possibly contributing to intra-tumour metabolic heterogeneity." (PMID 34572926, 2021). "It is important to note that for some miRNAs that bind to the mRNA of the MYC gene, a protective effect for tumor cells was also revealed." (PMID 34440124, 2021). "Comparison of the two different stem cells, tumor stem cells and normal stem cells, showed that the pathways of mTORC1, MYC signaling and oxidative phosphorylation, were positively enriched in tumor stem cells." (PMID 33898197, 2021). "In the low expression level of PTPRC, the genes were basically enriched in glycolysis, and typical tumor pathway including MYC-targets-V1 and MYC-targets-V2." (PMID 33520448, 2021). "During DMBA/TPA treatment, epidermal expression of MYCT58A (a degradation resistant mutant) decreases tumor latency and increases malignant transformation and metastasis compared to MYC overexpression." (PMID 34553848, 2021). "Being deregulated in up to 70% of human cancers, MYC inhibition can be in principle used against multiple types of tumor." (PMID 34359754, 2021). "Hart and colleagues showed that ER stress-mediated autophagy stimulated MYC-dependent transformation and tumour growth." (PMID 34445233, 2021). "Our findings uncovered a critical mechanism of epitranscriptome regulation by Wnt/β-catenin-mediated FTO downregulation and underscored the role of m6A modifications of MYC mRNA in regulating tumor cell glycolysis and growth." (PMID 33966037, 2021). "In the research of other solid tumors, some researchers pointed out that ALDOA mainly participates in the regulation of tumor development by involving in the regulation of cell signal transduction pathways, such as c-MYC/HIF-1 pathway 42, 43 or EMT pathway." (PMID 33994862, 2021). "Compound 13 showed significantly enhanced inhibition potency against MYC-amplified SCLCs than MYC-unamplifiedSCLCs and tumor growth inhibition activity in a cMYC-amplified SCLC cell line NCI-H446 xenograft mouse model when administeredintravenously." (PMID 34009981, 2021).
tumor (continued). "In PE/CA-PJ49 tumor cells treatment with RSV alone acted in an opposite way to the effect induced by CisPt alone on c-MYC gene expression." (PMID 34204834, 2021). "In mouse xenograft models of human TNBC, administration of C1572 suppressed tumor growth and depleted CSCs in a manner correlated with diminished MYC expression in residual tumor tissues." (PMID 34440080, 2021). "Transcriptome analysis showed paradoxical enrichment of MYC target genes in the MXD2/MXI1-NUTM1 tumor and promoted cell proliferation and anchorage-independent growth despite the lack of MYC expression, suggesting an “MYC-like” function." (PMID 34898574, 2021). "Dysfunctional apoptosis has been identified as a key to tumor development, especially in environments where oncogenes such as MYC drive tumor cell proliferation." (PMID 34103518, 2021). "Some tumor-related targets (MYC, E2F and G2M) and tumor-related biological processes (angiogenesis, epithelial-mesenchymal transition (EMT) and hypoxia) were enriched in m6A-C1." (PMID 34650549, 2021). "And to TMEgeneGroup2, G2M checkpoint, MYC targets v2 and oxidative phosphorylation were significantly up-regulated, indicating that cell cycle and tumor progression were activated in this group." (PMID 34954689, 2021). "Alisertib, an aurora kinase A/B inhibitor, has shown tumor suppression in SCLC cells with variant ASCL1 and MYC amplification in preclinical studies." (PMID 34531756, 2021). "STAT3 has been demonstrated to play multiple roles in cell growth, cell survival and tumour immunity through activating the transcription of various genes including c-MYC, CCND1 and Bcl-XL." (PMID 33531691, 2021). "NG25 reduced expression of MYC and E2F controlled genes, involved in tumor cell growth, cell cycle progression and drug resilience." (PMID 34676048, 2021). "The changes of c-MYC protein, another known stemness biomarker, were detected in the corresponding tumor tissues." (PMID 33934099, 2021). "Microarray mRNA expression analysis showed increasing ALYREF and MYC-signature gene expression throughout tumor progression in ganglia isolated from TH-MYCN+/+ mice in comparison to ganglia from wild-type littermates." (PMID 33767157, 2021). "FILNC1 is downregulated leading to increased c-MYC protein levels thereby increasing the glucose uptake, lactate production and tumor development." (PMID 33652661, 2021). "We assessed protein or mRNA expression of final targets of the Wnt/β-catenin pathway, such as WISP1, c-MYC, and MMP7, because of their tight association with tumor progression." (PMID 34233687, 2021). "Tumor cells differ from normal cells in the expression of a specific set of genes that are up- and downregulated by different levels of MYC." (PMID 33801599, 2021). "MYC has been defined as a tumour driver in PC and has been described to be overexpressed in the earliest phases of the disease, being a key precursor lesion to invasive prostatic adenocarcinoma." (PMID 33635497, 2021). "Overexpression of the c-MYC proto-oncogene contributes to tumor onset and/or progression, as indicated by findings in human tumors (that overexpress MYC in ~30% of cases) and mouse models." (PMID 33941777, 2021). "Hypoxia-inducible factor 1-alpha (HIF-1α) and vascular endothelial growth factor (VEGF) are two critical elements in tumor angiogenesis, and both are up-regulated upon MYC activation both in tumor cells and TAMs." (PMID 33081056, 2020). "Actually, tumour cells induce a MYC-mediated increase of LDH and Pyruvate kinase isoenzyme M2 expression levels causing a decrease in pyruvate levels." (PMID 32138158, 2020).